TBX5 (T-box transcription factor 5)
Diseases named in the same sentence as TBX5 in open-access papers (continued):
Sharing a sentence is not in itself a finding about the gene and the disease.
cardiomyopathy (7 papers, 2012 to 2024). A disease of the heart muscle or myocardium proper. "The patients with variants in the TBX5 gene showed severe cardiomyopathy phenotypes despite heterozygosity, while the mice with homozygous variant barely presented with compensatory chronic, decreasing cardiac contractility." (PMID 32236096, 2020). "Mutations found in cardiac troponin T type 2 (TNNT2) and T-box-5 (Tbx5) are implicated in cardiomyopathy." (PMID 22919414, 2012). "Our findings suggest that in addition to impacting the interaction of GATA4 with TBX5, the G296S mutation can also alter PGC-1α/ERRγ/GATA4 cooperativity which could contribute to the human disease phenotypes including cardiomyopathy which occurs in ERR-deficient mice." (PMID 35418170, 2022).
Tetralogy of Fallot (7 papers, 2017 to 2024). A congenital cardiac malformation comprising pulmonary stenosis, overriding aorta, ventricular septum defect, and right ventricular hypertrophy. "However, humans with TBX5 mutations also have other cardiac defects including tetralogy of Fallot (ToF), and rarely hypoplastic left heart syndrome (HLHS), but these defects are not observed in Tbx5 heterozygous mice." (PMID 35835508, 2022). "Consistent with these expression patterns, HOS patients with TBX5 mutations may have a number of significant heart defects, such as septal defects and certain complex malformations (tetralogy of Fallot (TOF), APVR and hypoplastic left heart)." (PMID 28761722, 2017). "TBX5.AS1 is significantly down-regulated in damaged heart tissue of tetralogy of Fallot." (PMID 33777735, 2021).
myocardial infarction (6 papers, 2013 to 2024). Gross necrosis of the myocardium, as a result of interruption of the blood supply to the area, as in coronary thrombosis. "Of particular interest, the recommendation to screen for HAND2 and TBX5 variants in families at risk for early and fatal myocardial infarcts." (PMID 28469241, 2017). "Two recent reports demonstrated that following myocardial infarction delivery of Gata4, Mef2c, and Tbx5, or GATA4, HAND2, MEF2C, and TBX5 in the injured myocardium successfully reprogrammed cardiac fibroblasts into cardiomyocytes." (PMID 23704920, 2013).
cardiac conduction disease (5 papers, 2018 to 2025). "Variants in TBX5, for example, are associated with HOS, classically consisting of upper-limb malformations, CHD and sometimes cardiac conduction disease." (PMID 36498454, 2022). "Collectively, these findings indicate that Tbx3 and Tbx5 coordinate to control VCS molecular fate and function, with implications for understanding cardiac conduction disorders in humans." (PMID 39257760, 2025).
cardiac hypertrophy (5 papers, 2022 to 2025). "Snhg7 induces ferroptosis (a form of iron-dependent cell death) and contributes to cardiac hypertrophy by interacting with T-box protein 5 (Tbx5), a critical TF for cardiac development and function." (PMID 39857701, 2025). "This suggests that TBX5 may be a target for drugs against cardiac hypertrophy since it will be more specific to the heart." (PMID 35207580, 2022). "However, TBX5, TBX20, ERBB4, and GRK5, which have been linked to the proliferation of fetal and neonatal cardiomyocytes [TBX5, TBX20, ERBB4] and cardiac hypertrophy [GRK5], were upregulated in the CM1 cluster, as well as in Fetal cardiomyocytes." (PMID 35860330, 2022). "This resulted in the identification of KLF-4 interactions with genes like GATA4, MEF2C, TBX5, NKX2.5, and SRF, all of which are known regulators of cardiac hypertrophy and pro-hypertrophic pathways." (PMID 38672763, 2024). "LncSnhg7 interacts with T-box transcription factor 5 (Tbx5) to transcriptionally induce GLS2 expression, resulting in the promotion of cardiomyocyte ferroptosis in cardiac hypertrophy." (PMID 37686142, 2023).
congenital heart defects (5 papers, 2010 to 2023). "The TBX5 gene regulates morphological changes during heart development, and it has been associated with epigenetic abnormalities observed in congenital heart defects (CHD)." (PMID 35053095, 2022).
prostate carcinoma (5 papers, 2013 to 2025). A carcinoma that arises from epithelial cells of the prostate gland. "This case outlines the diagnosis, management, and treatment sequelae of an individual with prostate cancer and a known TBX5 T-box transcription factor mutation." (PMID 23984174, 2013). "Although this is the first case of prostate cancer reported in a patient with the TBX5 mutation, it has been demonstrated that T-box transcription factors have an important role in metastasis in murine models of prostate carcinoma." (PMID 23984174, 2013). "The first cluster is composed of ZNF740, AR, and TBX5, which are implicated in prostate cancer." (PMID 40453647, 2025).
ulnar-mammary syndrome (5 papers, 2016 to 2026). Ulnar-mammary syndrome (UMS) is a rare developmental disorder characterized by ulnar defects, mammary and apocrine gland hypoplasia and genital anomalies. "Several human T-box genes show haploinsufficiency in the limb, including Tbx5 and Tbx3 that, when mutated, cause Holt-Oram and ulnar-mammary syndrome, respectively." (PMID 41981936, 2026). "In a large German family, TBX3 and TBX5 duplication was reported to be associated with Ulnar-Mammary syndrome." (PMID 35565484, 2022).
AV block (4 papers, 2013 to 2024). "TBX3 and TBX5 can jointly mark the cardiac conduction system, and TBX5 knockout mice show abnormal heart rates, such as sinus arrest, AV block and ventricular tachycardia." (PMID 35851424, 2022).
colorectal cancer (4 papers, 2015 to 2023). A primary or metastatic malignant neoplasm that affects the colon or rectum. "In tumors, Tbx5 inhibits proliferation in osteosarcoma, acts as a tumor suppressor in lung cancer, and is epigenetically inhibited in colorectal cancer." (PMID 38110859, 2023).
dilated cardiomyopathy (4 papers, 2019 to 2024). Cardiomyopathy which is characterized by dilation and contractile dysfunction of the left and right ventricles. "Moreover, in patients with dilated cardiomyopathy, there is an altered methylation pattern in the regulatory regions of cardiac development genes, such as T-box protein 5 (TBX5), heart and neural crest derivatives expressed 1 (HAND1), and NK2 homeobox 5 (NKX2.5)." (PMID 31649728, 2019).
gastric cancer (4 papers, 2015 to 2024). A primary or metastatic malignant neoplasm involving the stomach. "High expression of TBX5 had been verified to be related with low survival rate of stage I and II gastric cancer patients." (PMID 38413457, 2024). "The aim of the present study was to investigate TBX5 expression and its potential clinical significance in gastric cancer (GC)." (PMID 26622790, 2015).
heart failure (4 papers, 2020 to 2024). Inability of the heart to pump blood at an adequate rate to meet tissue metabolic requirements. "For instance, TBX5 is critical for cardiac function and its expression is dysregulated in the ventricular myocardium of heart failure patients." (PMID 39095802, 2024). "Preclinical data underscore the cardioprotective role of Tbx5 upon heart failure." (PMID 36869039, 2023). "In our study, inhibition of TBX5 was shown to dysregulate several genes such as DES, NKX2-5, ACTC1, MYH6, ATP2A2 and HSPB7, which further contributed to ICM-related diseases such as failure of heart and degeneration of heart." (PMID 32423033, 2020). "TBX5-regulated NKX2-5 is involved in heart formation and development and dysregulated NKX2-5 could lead to heart failure and sudden cardiac death." (PMID 32423033, 2020). "Indeed, varying levels of albinism, heart defects, and heart failure related edema depending on the corresponding gene disruption efficiency (effective frameshifts) were observed in SaCas9- or KKH SaCas9-mediated tyr and tbx5 disruption, respectively." (PMID 35804405, 2022).
lung adenocarcinoma (4 papers, 2018 to 2024). A carcinoma that arises from the lung and is characterized by the presence of malignant glandular epithelial cells. "Lastly, TBX5 was reduced by 2.5-fold in lung adenocarcinoma, and by fourfold in lung squamous cell carcinoma." (PMID 38413457, 2024). "Our results showed that signatures from TBX3 and TBX5 are significantly anti-correlated with lung adenocarcinoma signatures from patients (p < 0.05)." (PMID 30425966, 2018). "Finally, the protein expression of TBX5 decreased by twofold and 2.5-fold in lung adenocarcinoma and lung squamous cell carcinoma.The result showed that the TBX2 subfamily had low expression in both lung squamous cell carcinoma and lung adenocarcinoma." (PMID 38413457, 2024). "TBX5.AS1 has been found to be a prognostic factor for lung adenocarcinoma." (PMID 33777735, 2021). "TBX5 and TBX3 were highly expressed in normal lungs, but significantly suppressed in lung adenocarcinoma." (PMID 34262872, 2021).
Osteochondrosis (4 papers, 2013 to 2025). Abnormal growth ossification centers in children. "The TBX5 gene is more important for limb and heart development and is associated with animal welfare, for example, osteochondrosis, in the pig industry." (PMID 40495150, 2025).
Arthritis (3 papers, 2018 to 2019). Inflammation of a joint. "We conclude that miR‐10a‐5p in a relation with TBX5 regulates joint inflammation in arthritis, which would serve as a diagnostic and therapeutic target for RA treatment." (PMID 28782180, 2018). "In the current study, we showed that B10.RIIIS/J-Eae39r2 sub-congenic mice (with Tbx3, Tbx5 and Rbm19 in the sub-congenic fragment) develop more severe arthritis compared to the control mice." (PMID 30630509, 2019). "We found that miR-10a-5p targeting TBX5 play their role in joint inflammation." (PMID 29545315, 2018). "Summarily, we have proved that TBX5 regulated by miR-10a-5p could promote synoviocyte proliferation and suppress apoptosis, which reveals a new mechanism of miR-10-5p and its target TBX5 in arthritis." (PMID 29545315, 2018). "However, little was known about the role of TBX5 in arthritis before." (PMID 29545315, 2018). "Thus, miR-10a-5p might modulate cell apoptosis, the proliferation of synoviocytes via targeting TBX5, which is an important supplementary mechanism to miR-10a-5p in arthritis." (PMID 29545315, 2018).
asthma (3 papers, 2013 to 2023). "In addition, the Tbx5 was reported to be associated with asthma susceptibility in the developing lung in rat models." (PMID 23527081, 2013).
cholangiocarcinoma (3 papers, 2016 to 2020). A carcinoma that arises from the intrahepatic biliary tree (intrahepatic cholangiocarcinoma) or from the junction, or adjacent to the junction, of the right and left hepatic ducts (hilar cholangiocarcinoma). "The FGFR1 gene has been suggested as a target of YAP in cholangiocarcinoma, as chromatin immunoprecipitation assays demonstrated the simultaneous nuclear presence of TBX5-YAP complexes on the promoter region of FGFR1." (PMID 31963871, 2020). "Thus, it is likely that YAP and TBX5 form a complex to regulate FGFR1 expression, similar to those described in cholangiocarcinoma." (PMID 31963871, 2020).
diabetes (3 papers, 2014 to 2024). "However, other cardiac transcription factors including Nkx2.5, Mef2c and Tbx5 were not significantly altered by maternal diabetes or NAC treatment." (PMID 24533448, 2014).
heart-hand syndrome (3 papers, 2016 to 2022). Heart-hand syndrome refers to a group of congenital disorders characterized by malformations of the upper limbs and heart. "Given that the patient's clinical diagnosis was heart-hand syndrome, we screened the TBX5, SALL4, and LMNA genes, but no deleterious variation was found." (PMID 34485408, 2021).
osteosarcoma (3 papers, 2006 to 2023). A usually aggressive malignant bone-forming mesenchymal neoplasm, predominantly affecting adolescents and young adults. "Ectopic expression of TBX5 in osteosarcoma cells inhibits cell proliferation and induces apoptosis." (PMID 17173667, 2006).
pulmonary stenosis (3 papers, 2020 to 2023). "TBX5 variants in eight individuals from four unrelated families were also correlated with familial dilated cardiomyopathy and atrial septal aneurysm along with tricuspid atresia and pulmonary stenosis, which represented a novel phenotype that may have other underlying mechanisms." (PMID 36936432, 2023). "Notably, previous studies have causally linked TBX5 variations tovarious cardiovascular malformations, including ASD, VSD, atrioventricular septaldefect, pulmonary stenosis, hypoplastic left ventricle, mitral valve anomaly." (PMID 33306779, 2020).
synovial sarcoma (3 papers, 2018 to 2022). "The expression of miR‐10a‐5p and TBX5 in the synovium of RA and human synovial sarcoma cell line SW982 stimulated by IL‐1β was determined by RT‐qPCR and Western blotting." (PMID 28782180, 2018). "Human synovial sarcoma cell line, SW982 cells stimulating with interleukin-1β (IL-1β) were transfected with miR-10a-5p mimic and siRNA of TBX5." (PMID 29545315, 2018). "Stimulation of the human synovial sarcoma cell line SW982 with IL-1β inhibits the expression of miR-10a, leading to the up-regulation of its target gene, T-box transcription factor 5 (TBX5), which induces the proliferation of synoviocytes and suppression of synoviocyte apoptosis in RA." (PMID 36555120, 2022).
ventricular tachycardia (3 papers, 2022 to 2025). A disorder characterized by an electrocardiographic finding of three or more consecutive complexes of ventricular origin with a rate greater than a certain threshold (100 or 120 beats per minute are commonly used). "Moreover, VCS-specific Tbx5 knockout caused slowed VCS function and ventricular tachycardia (VT) resulting in sudden death in mice, emphasizing the importance of Tbx5 in VCS conduction." (PMID 40705007, 2025). "Moreover, VCS-specific Tbx5 knockout caused slowed VCS function and ventricular tachycardia resulting in sudden death in mice, emphasizing the importance of Tbx5 in VCS conduction." (PMID 39257760, 2025). "Removal of both Tbx3 and Tbx5 from the adult VCS resulted in increased episodes of spontaneous ventricular tachycardia (VT)." (PMID 39257760, 2025). "Taken together, these data indicate that the conduction defect and ventricular tachycardia observed in mice with VCS-specific Tbx3:Tbx5 deletion occur prior to the onset of left ventricular dysfunction or evidence of remodeling, implying a primary origin." (PMID 39257760, 2025). "Combined Tbx3 and Tbx5 deficiency in the adult VCS led to conduction defects, including prolonged PR and QRS intervals and elevated susceptibility to ventricular tachycardia." (PMID 39257760, 2025). "Loss of Tbx3 and Tbx5 expression in the mature VCS led to profound conduction defects, characterized by prolonged PR interval and QRS duration, increased susceptibility to ventricular tachycardia, and sudden death." (PMID 39257760, 2025).
acro-renal-ocular syndrome (2 papers, 2019 to 2023). "In zebrafish, SALL4 acts downstream of TBX5 and is required for pectoral fin outgrowth; mutations at the SALL4 locus on chromosome 20 resulted in a range of clinically overlapping phenotypes, including Okihiro syndrome, HOS, acro-renal-ocular syndrome, and thalidomide embryopathy." (PMID 36936432, 2023).
cardiac septal defect (2 papers, 2019 to 2022). "This study designed to study the association of five single–nucleotide variants of NKX2‐5, GATA4, and TBX5 genes with sporadic nonsyndromic cases of a congenital cardiac septal defect in Egyptian children." (PMID 30834692, 2019). "The analysis of Receiver Operating Characteristic (ROC) showed that the methylation levels of the TBX5 gene could be used as a risk marker for congenital septal defects (AUC = 0.68, 95% CI = 0.56–0.80; p = 0.004)." (PMID 35053095, 2022). "As far as we know, this the first study with an approach that included congenital septal defect patients and the TBX5 gene; however, various investigations have been carried out in patients with TOF, with different genes implicated in cardiogenesis." (PMID 35053095, 2022).
clubfoot (2 papers, 2016 to 2021). The most common congenital deformation of the foot, occurring in 1 of 1,000 live births. "Notably, haploinsufficiency causes these human syndromes, and clubfoot is partially penetrant in Pitx1+/- mice, collectively pointing to an exquisite sensitivity of limb morphology to levels of Pitx1 and Tbx5 gene products." (PMID 26977633, 2016).
coronary artery disease (2 papers, 2017 to 2024). "We documented a novel interaction between TBX5 and HAND2, and showed that a p.G202V HAND2 variant associated with CHD and coronary artery diseases found in a large Lebanese family with high consanguinity, drastically inhibited this interaction by 90%." (PMID 28469241, 2017). "In contrast, and of particular interest is the coronary artery disease problem which could be explained by the defective interaction of the p.G202V HAND2 protein with TBX5." (PMID 28469241, 2017).